ENSG00000258677 (novel  protein, UBE2W-STAU2 readthrough)
Gene: Protein-coding gene on chromosome 8 (73,688,691 to 73,878,854, reverse strand). Ensembl gene ENSG00000258677.
Genetic constraint (gnomAD): Missense variants: 61 observed, 121.11 expected, observed/expected ratio (o/e) 0.5, 90% interval 0.41 to 0.62. Synonymous variants: 39 observed, 40.39 expected, observed/expected ratio (o/e) 0.97, 90% interval 0.75 to 1.26.